PML (PML nuclear body scaffold)
Diseases named in the same sentence as PML in open-access papers (continued):
Sharing a sentence is not in itself a finding about the gene and the disease.
viral infection (continued). "Given the known functions of the PML bodies during viral infections and in view of their well-known dot-like nuclear distribution, we examined potential colocalization of UBF with PML bodies during lytic reactivation." (PMID 36016343, 2022). "PML NBs are dynamic structures harboring a few permanent resident proteins (e.g., PML, Sp100, and SUMO) and numerous transient proteins depending on cell stimulation (i.e., stress, IFN, or viral infection)." (PMID 33968942, 2021). "PML nuclear bodies (NBs) are membrane-free subnuclear compartments whose formation is initiated and controlled by the PML protein, a member of the tripartite motif (TRIM) family, which is upregulated in viral infections by type I and type II interferons." (PMID 35052571, 2021). "Similar dual anti-viral and pro-viral effects have recently been reported for PML, and the H3.3-specific chaperone, HIRA, has been shown to both enhance and restrict viral infection depending on context." (PMID 30465651, 2018). "PML-NB components PML, SP100, DAXX and ATRX are bona fide restriction factors for viral infection and members of different virus families have evolved sophisticated mechanisms to bypass PML-NB-mediated immunity." (PMID 29065450, 2017). "They revealed that PML and DAXX knock-down leads to a reduction in HPV18 transcription, while SP100 behaves as a repressor of viral infection." (PMID 26148509, 2015). "Previous studies have established critical functions for PML bodies in mediating defense, IFN-dependent immunological and apoptotic responses to viral infection." (PMID 25665578, 2015). "Several ND10 components, like PML, Sp100, Daxx and ATRX have been shown to be part of a cellular defense mechanism against viral infection and therefore became targets of viral effector proteins." (PMID 24453968, 2014). "Our results demonstrate that PML, an ISG product with a broad intrinsic antiviral activity, is also able to trigger IFN-β synthesis upon viral infection." (PMID 24586174, 2014). "Among the six nuclear PML isoforms (PMLI to PMLVI), only PMLIV sequesters the ORF23 capsid protein in PML NBs in infected cells and significantly inhibits viral infection." (PMID 23734343, 2013). "PML IV significantly inhibited viral infection and interacted with the ORF23 capsid surface protein, which was identified as a target for PML-mediated NC sequestration." (PMID 21304940, 2011). "Similar to previous studies, we observed that IFN treatment caused re-localization of HIRA to PML-NBs in NIKS keratinocytes and this is independent of viral infection or cellular senescence." (PMID 40568077, 2025). "Moreover, PML targeting by IE1 is thought to promote HCMV replication, partially by inhibiting PML-dependent IFN and ISG expression triggered by viral infection." (PMID 40143325, 2025). "MLOs include nuclear PML bodies (also known as ND10)—compartments involved in the regulation of cellular metabolism, transcription, the maintenance of genome stability, responses to viral infection, apoptosis, and tumor suppression." (PMID 38136675, 2023). "Thus, we expand the panel of previous results on core-PML protein interaction by proving SUMO PTM-dependent binding and colocalization of wt HBV core at PML-NBs during virus infection of differentiated hepatocytes." (PMID 37199632, 2023).
viral infection (continued). "While senescence was the first stress shown to induce accumulation of HIRA complex in PML NBs, IFN-I signaling pathway was recently shown to be responsible for similar behavior of HIRA upon a viral infection." (PMID 37227756, 2023). "For example, PML-NBs epigenetically modify the genomes of human herpes simplex virus type 1 (HSV-1) and human cytomegalovirus (HCMV), resulting in silencing of the viral genomes during the early stages of virus infection." (PMID 34888375, 2021). "PML targeting by IE1 is thought to promote hCMV replication in at least two ways: by relieving viral transcription from repression mediated by PML proteins or PML bodies (intrinsic immunity) and by inhibiting PML-dependent IFN and ISG expression triggered by viral infection (innate immunity)." (PMID 32365141, 2020). "The level of autophagosomes and LC3-II/I ratio in the mock-infected and EV71-infected PML−/− cells were similar, suggesting that autophagy was mainly induced by PML knockout and not further induced by the viral infection." (PMID 29922292, 2018). "In this study, the high levels of autophagy in the PML−/− cells were independent of the cellular stress conditions (serum deprivation or viral infection), suggesting that PML plays a vital role in autophagy regulation." (PMID 29922292, 2018). "Notably, the expressions of PML-NB components such as PML and SP100 themselves are also induced by the interferon pathway, corroborating their crucial role in the intrinsic immunity to viral infection." (PMID 29065450, 2017). "Considering that PML-NBs are also recognized as transcriptional regulatory elements and post-translational modification platforms, and become enlarged during ASFV infection, the role of PML protein on the viral infection progression was evaluated." (PMID 26389938, 2015). "In addition, we show here that PML enhanced both IRF3 activation and IFN-β synthesis upon viral infection." (PMID 24586174, 2014). "Recent evidence suggests that NB proteins independently contribute to the repression of herpesvirus replication, raising the concept that individual NB components, rather than the PML-NB structure as a whole, restrict viral infections." (PMID 25412268, 2014). "PML NBs are dynamic structures, which harbor a few permanently (PML, Sp100, and SUMO) and numerous transiently residing proteins depending on different conditions (i.e., transformation, stress, interferon (IFN) treatment, and viral infections)." (PMID 23734343, 2013). "Besides PML-III, PML-IV is also known to restrict viral infections, such as VZV, EMCV, and rabies virus, either through a so far unknown mechanism or by simply sequestering viral proteins to the PML-NBs." (PMID 35699431, 2022). "Intrinsic resistance is a crucial line of defense against virus infections, and members of the Tripartite Ring Interaction Motif (TRIM) family of proteins are major players in this system, such as cytoplasmic TRIM5α or nuclear promyelocytic leukemia (PML/TRIM19) protein." (PMID 33524065, 2021). "PML playing a regulation of autophagy in viral infection has not been previously reported." (PMID 29922292, 2018). "Although we cannot completely exclude additional, later mechanisms, the PML-mediated block to RT and nuclear import mirrors the magnitude of restriction measured in HIV-GFP infectivity assays, suggesting that this early restriction is the most relevant block in HIV reporter virus infection." (PMID 26703718, 2015). "Having shown that hIE1CORE binds with high affinity to and deSUMOylates PML, but fails to disrupt PML accumulations, it was important to investigate whether this is sufficient to antagonize PML-NB mediated repression of viral infection." (PMID 25412268, 2014).
viral infection (continued). "There were some background γH2AX signals in PML bodies without virus infection." (PMID 20359340, 2010). "Thus, PML knockout resulted in higher autophagy, which was not affected by the viral infection." (PMID 29922292, 2018). "However, in contrast to HFFs, we could not detect a significantly enhanced HIV reporter virus infection in Jurkat cells upon PML knockdown." (PMID 26703718, 2015). "Additionally, some but not all viral infections can abolish PML SUMOylation." (PMID 23316480, 2012). "Although a great deal of evidence supports the theory that ND10 components such as PML, Daxx, and SP100 are viral gene repressors and protect host cells against many viruses, the effects of the ND10 structure on viral infection have been not determined." (PMID 21552525, 2011).
breast carcinoma (55 papers, 2011 to 2025). "To investigate the molecular mechanisms underlying the involvement of PML in cell proliferation and self‐renewal pathways in breast cancer, we used the PMLIV isoform since it is associated with apoptosis, senescence, and DNA damage." (PMID 30927552, 2019). "This study further demonstrated that PML provides a selective advantage in response to metabolic stress triggered by conditions of loss of attachment in breast cancer cells." (PMID 23936764, 2013). "In humans, PML deficiency occurs commonly in a broad spectrum of human cancers including lung, prostate and breast carcinoma, lymphomas, CNS tumors, and germ cell tumors, through a mechanism that involves aberrant ubiquitin-mediated degradation." (PMID 23526763, 2013). "In addition, complete or partial loss of PML protein expression has been observed in multiple human cancer types, such as prostate and colon adenocarcinoma, breast carcinoma, lymphoma, CNS tumors, and germ cell tumors." (PMID 23526763, 2013). "The alternative splicing of PML precursor mRNA gives rise to various PML isoforms, yet their expression profile in breast cancer cells remains uncharted." (PMID 37720048, 2023). "ChIP-seq analysis reveals significant overlap between PML-, ER-, and Myc-bound promoters, suggesting their coordinated regulation of target gene expression, including genes involved in breast cancer stem cells (BCSCs), such as JAG1, KLF4, YAP1, SNAI1, and MYC." (PMID 37720048, 2023). "Our findings challenge the conventional understanding of PML as a tumor suppressor, redefine its role as a promoter of tumor growth in breast cancer and offer new insights into the unique roles of PML isoforms in breast cancer." (PMID 37720048, 2023). "PML expression promoted tumour cell invasion in vitro and was correlated with poor prognosis in breast cancer patients." (PMID 36701089, 2023). "Consistently, the upregulation of PML SUMO-2/3 modification has been observed in metastatic breast cancer cells." (PMID 33968766, 2021). "For instance, reduced expression of PML was found to promote multiple tumor growth, including prostate adenocarcinoma, breast carcinoma, and thyroid carcinoma." (PMID 34188683, 2021). "The identification of PML as a novel target in aggressive breast cancer tumors prompted us to investigate the molecular consequences of its inhibition in an established cell culture." (PMID 31570853, 2020). "In breast cancer, PML regulates aggressiveness and metastatic features through the control of the stem cell gene, SOX9, and the Hypoxia-inducible factor 1 alpha (HIF1α) signaling." (PMID 31570853, 2020). "Pin1 binds and targets PML for degradation in an ERK-dependent manner by targeting Ser403 and Ser505 of PML, inducing the development of breast cancer cells." (PMID 32296699, 2020). "The contribution of PML in maintaining stemness and breast cancer metastasis provides a promising strategy in targeting PML towards a more context-dependent effective therapy." (PMID 33396222, 2020). "In line with this notion, we found that PML is associated to the promoter regions of MYC and PIM1, consistent with their direct correlation in breast cancer specimens." (PMID 31570853, 2020). "In turn, stable expression of PML in telomerase-primed MCF7 breast cancer cells also results in ALT, whereas ectopic expression of hTERT in primary ALT cells maintains their telomeres with both TMMs." (PMID 32316332, 2020). "In accordance with the pro-survival role of PML in breast cancer, PML is upregulated in TNBC, a subset of breast cancers." (PMID 33396222, 2020). "PMLIV overexpression significantly decreased sphere formation efficiency of MDA‐MB‐231 cells, implying that PML inhibits the self‐renewal of breast cancer stem cells." (PMID 30927552, 2019).
breast carcinoma (continued). "Both mRNA and protein expression of PML were increased in response to ERβ overexpression on multiple human breast cancer cell lines." (PMID 31506431, 2019). "To study the role of PML in breast cancer, we first examined the expression levels of PML in breast cancer cell lines of different molecular subtypes." (PMID 30927552, 2019). "Putting this literature into our perspective we sought out to understand how PML gene is regulated in breast cancer." (PMID 31506431, 2019). "We found that clinical expression of PML positively correlates with that of ERβ both in normal and breast carcinoma samples and inversely correlates with markers of cellular proliferation, hinting towards a possible mechanistic interdependence." (PMID 31506431, 2019). "This study aims to uncover an unidentified mechanism of PML gene regulation and its stabilization in breast cancer via ERβ signalling and the impact on cellular apoptosis." (PMID 31506431, 2019). "Collectively, our study identifies ERβ signalling as a novel mechanism for PML gene regulation in ERα− breast cancer." (PMID 31506431, 2019). "To further dissect PML's role in breast cancer growth, we performed genome‐wide expression analysis on PMLIV OE and control cells (GSE119583)." (PMID 30927552, 2019). "As PML was recently identified as an upstream activator of PGC-1α in breast cancers, we tested the impact of PML silencing on PGC-1α in high-OXPHOS OCCLs." (PMID 30244973, 2019). "Along these lines it was also demonstrated that PML targeting impacts on breast cancer (BCa)-initiating cell function, and hence on cancer initiation and dissemination in BCa." (PMID 29888200, 2018). "PML expression is strongly associated with TNBC and basal high tumor-grade breast cancers, which are among the most undifferentiated and untreatable breast cancers." (PMID 23847764, 2013). "We modeled our investigation of these questions by first translating the known role that PML plays in breast cancer to a similar possible role in stem cell biology." (PMID 23504288, 2013). "The PML-PPARδ-FAO pathway in primary breast cancer cells grown in methylcellulose renders these cells resistant to anoikis, which results in luminal filling in a 3D basement membrane breast culture model." (PMID 23504288, 2013). "As part of this developing picture of how breast cancer is fueled, we have recently identified a tumoral metabolic reprograming for PML that is central to breast cancer cell survival." (PMID 23504288, 2013). "PML is highly expressed in a subset of breast cancers with worse prognosis and shorter time to recurrence." (PMID 23936764, 2013). "PML is consistently enriched in triple-negative cases, and PML expression in breast cancer correlates with both activated PPAR signaling and reduced time to recurrence, a gene signature of poor prognosis." (PMID 23504288, 2013). "Regulation of cell migration: PML was recently found to inhibit the migration of MDA-MB231 breast cancer cell lines by downregulating the expression of integrin β1." (PMID 22935031, 2012). "In 2008, Shimada proposed the effect of two PKM2 gene and PML tumor suppressor protein breast cancer." (PMID 24551779, 2012). "Afterward, we examined the mRNA expression levels of ZBTB16 and PML in breast cancer tissues." (PMID 38110365, 2023). "In addition, activated STAT3 levels are known to correlate with promyelocytic leukemia (PML) gene expression in several tumor models, including breast cancer, where it acts as an upstream regulator of PML." (PMID 35562901, 2022). "With this data in mind, we first evaluated the association of PML, MYC, and PIM1 in breast cancer." (PMID 31570853, 2020). "To ascertain whether the “addiction” was restricted to TNBC cells, we took advantage of various breast cancer cell lines belonging to distinct subtypes with differing levels of PML." (PMID 31570853, 2020).